COQ6 (coenzyme Q6, monooxygenase)
Description:
FAD-dependent monooxygenase required for two non-consecutive steps during ubiquinone biosynthesis. Required for the C5-ring hydroxylation during ubiquinone biosynthesis by catalyzing the hydroxylation of 4-hydroxy-3- (all-trans-decaprenyl)benzoic acid to 3,4-dihydroxy-5-(all-trans-decaprenyl)benzoic acid. Also acts downstream of COQ4, for the C1-hydroxylation during ubiquinone biosynthesis by catalyzing the hydroxylation of 2-methoxy-6-(all-trans-decaprenyl)phenol to 2-methoxy-6-(all-trans-decaprenyl)benzene-1,4-diol. The electrons required for the hydroxylation reaction are funneled indirectly to COQ6 from NADPH via a ferredoxin/ferredoxin reductase system composed of FDX2 and FDXR.
Synonyms: CGI-10; CGI10; COQ10D6
Tractability: Antibody: UniProt places it where antibodies can reach, with medium confidence. PROTAC: ubiquitination databases record sites on it; its protein half-life has been measured.
Gene: Protein-coding gene on chromosome 14 (73,949,926 to 73,963,670, forward strand). Ensembl gene ENSG00000119723.
Subcellular location: Mitochondrion inner membrane; Golgi apparatus; Cell projection
Pathways (Reactome):
Metabolism: Ubiquinol biosynthesis
Gene Ontology:
Molecular function: 2-methoxy-6-polyprenolphenol 4-hydroxylase activity; 4-hydroxy-3-all-trans-polyprenylbenzoate oxygenase activity; protein binding; oxidoreductase activity; FAD binding; flavin adenine dinucleotide binding; monooxygenase activity; oxidoreductase activity, acting on paired donors, with incorporation or reduction of molecular oxygen; oxidoreductase activity, acting on paired donors, with incorporation or reduction of molecular oxygen, NAD(P)H as one donor, and incorporation of one atom of oxygen; oxidoreductase activity, acting on paired donors, with incorporation or reduction of molecular oxygen, reduced flavin or flavoprotein as one donor, and incorporation of one atom of oxygen
Biological process: ubiquinone biosynthetic process
Cellular component: mitochondrial inner membrane; mitochondrion; ubiquinone biosynthesis complex; extrinsic component of mitochondrial inner membrane; Golgi apparatus
Genetic constraint (gnomAD): Loss-of-function variants: 42 observed, 55.88 expected, observed/expected ratio (o/e) 0.75, 90% interval 0.59 to 0.97. The upper end of that interval is the gene's LOEUF score, 0.97, which puts it in group 4 of 6, group 1 being the genes least tolerant of losing a copy. Missense variants: 542 observed, 608.16 expected, observed/expected ratio (o/e) 0.89, 90% interval 0.83 to 0.96. Synonymous variants: 205 observed, 233.72 expected, observed/expected ratio (o/e) 0.88, 90% interval 0.78 to 0.99.
Gene-disease validity (ClinGen):
ClinGen rates the evidence that COQ6 causes each of these diseases.
primary coenzyme Q10 deficiency 8 (autosomal recessive): Definitive. Any coenzyme Q10 deficiency in which the cause of the disease is a mutation in the COQ7 gene.
Homologues: Orthologues: chimpanzee COQ6 (99% identical), macaque COQ6 (98% identical), dog COQ6 (92% identical), rabbit COQ6 (90% identical), guinea pig COQ6 (90% identical), pig COQ6 (90% identical), mouse Coq6 (87% identical), rat Coq6 (87% identical), tropical clawed frog coq6 (65% identical), zebrafish coq6 (64% identical), Drosophila melanogaster Coq6 (39% identical), Caenorhabditis elegans coq-6 (36% identical). Paralogues in human: KMO (18% identical).
Diseases named in the same sentence as COQ6 in open-access papers:
COQ6 is named in the same sentence as 42 diseases in open-access papers, as found by Europe PMC text mining. Sharing a sentence is not in itself a finding about the gene and the disease. The quoted sentences say what the papers report.
Nephropathy (5 papers, 2017 to 2025). A nonspecific term referring to disease or damage of the kidneys. "Complete remission of proteinuria was more frequently observed in patients with renal disease resulting from COQ6 mutations." (PMID 37627647, 2023). "Widmeier and his colleagues utilized podocyte-specific, Adck4- and coq6- knockout mouse models to clarify reduced respiratory chain activity and mitochondrial potential in the CoQ10 nephropathy model." (PMID 39805995, 2025). "Previous research reported that CoQ10 nephropathy due to mutations in genes such as PDSS2, COQ2, COQ6, and COQ8B is identified in approximately 1–2.7% of SRNS cases." (PMID 39805995, 2025).
nephrotic syndrome (5 papers, 2018 to 2023). A collection of symptoms that include severe edema, proteinuria, and hypoalbuminemia; it is indicative of renal dysfunction. "Primary CoQ10 deficiency due to COQ6 mutations should be considered in children presenting with both steroid-resistant nephrotic syndrome and sensorineural hearing loss." (PMID 37627647, 2023). "The rescue in the phenotypes of the Coq6podKO and Adck4ΔPodocyte KO mice after the treatment with 2,4-diHB suggests a potential treatment strategy for nephrotic syndrome resulting from COQ6 and ADCK4 mutations." (PMID 34829558, 2021). "Genetic defects in COQ6 gene cause renal and neurological manifestations of primary CoQ10 deficiency, like steroid resistant nephrotic syndrome, cerebellar ataxia, seizures and mental retardation." (PMID 33527138, 2021). "The COQ6 gene mutations that cause a CoQ10 deficiency led to the nephrotic syndrome." (PMID 30594156, 2018).
coenzyme Q10 deficiency (4 papers, 2020 to 2024). A genetically heterogeneous condition, typically inherited in an autosomal recessive fashion, characterized by coenzyme Q10 deficiency. "In conclusion, CoQ10 deficiency caused by COQ6 mutations is a rare cause of SRNS with variable neurological, renal, hearing, and optical impairment." (PMID 32685349, 2020). "Our study reports the cases of two brothers of Turkish origin with renal failure and sensorineural deafness associated with COQ6 mutations responsible of CoQ10 deficiency." (PMID 32685349, 2020). "In this study, we report on the cases of two brothers from a consanguineous Turkish couple who both presented a primary CoQ10 deficiency caused by a COQ6 mutation." (PMID 32685349, 2020). "Genetic analysis of patient 1 revealed primary Coenzyme Q10 deficiency caused by a COQ6 mutation." (PMID 32685349, 2020). "Coenzyme Q10 deficiency can result from pathogenic variants in the COQ2, COQ4, COQ6, COQ8A, or COQ8B gene." (PMID 38570878, 2024). "Moreover, the spectrum of symptoms of encephalopathy, intellectual disability, seizures, and muscle involvement has been described in patients with variants responsible for other primary coenzyme Q10 deficiency (COQ2, COQ4, COQ6, COQ7, COQ9) as well as in patients with COQ8A-ataxia." (PMID 36295857, 2022).
steroid-resistant nephrotic syndrome (4 papers, 2018 to 2022). Nephrotic syndrome, occurring in the pediatric population, in which proteinuria does not normalize with administration of steroids; this condition is unresponsive to a minimum of four weeks administration of oral corticosteroids. "Mutations in the human COQ6 gene are associated with primary CoQ10 deficiency and are further associated with several disease states, predominantly steroid-resistant nephrotic syndrome (SRNS) and sensorineural hearing loss (SNHL)." (PMID 36552517, 2022). "Primary coenzyme Q10 deficiency-6 (COQ10D6) is an autosomal recessive disorder attributable to biallelic COQ6 variants; the cardinal phenotypes are steroid-resistant nephrotic syndrome (SRNS), which inevitably progresses to kidney failure, and sensorineural hearing loss (SNHL)." (PMID 36124066, 2022). "Among the so far studied genes, 4: PDSS2/COQ1, COQ2, COQ6, and ADCK4/COQ8B are associated with steroid-resistant nephrotic syndrome (SRNS)—they are mutated in about 1% of cases." (PMID 30232548, 2018). "As steroid-resistant nephrotic syndrome (SRNS) has been linked to mutations in several genes encoding CoQ biosynthetic enzymes, a podocyte-specific Coq6 KO mouse model was generated by crossing Podocin-cre mice with Coq6loxP/loxP mice in which two loxP sites surround exon 6 in the Coq6 gene." (PMID 34829558, 2021).
Primary coenzyme Q10 deficiency-6 (3 papers, 2021 to 2023). "Primary coenzyme Q10 deficiency-6 (COQ10D6) is an autosomal recessive disorder attributable to biallelic COQ6 variants (OMIM # 614650)." (PMID 36124066, 2022). "COQ6 deficiencies mainly cause a renal phenotype that may be associated with deafness or visual impairment (primary coenzyme Q10 deficiency-6; COQ10D6; OMIM #614650)." (PMID 36978966, 2023). "Primary coenzyme Q10 deficiency-6 (COQ10D6), as a rare autosomal recessive disease caused by COQ6 mutations, is characterized by progressive infantile-onset nephrotic syndrome resulting in end-stage renal failure and sensorineural hearing loss." (PMID 35111204, 2021).
schwannomatosis (3 papers, 2022 to 2025). The least frequent form of the rare genetic disorder neurofibromatosis. "This mutation is reported to lead to haploinsufficiency of COQ6, predisposing individuals harboring the mutation to schwannomatosis, which is a rare genetic disorder resulting in multiple benign schwannomas growing on peripheral nerves." (PMID 36552517, 2022). "In contrast to DGCR8, evidence supporting the involvement of variants in CDKN2A and COQ6 in schwannomatosis pathogenesis is less conclusive." (PMID 35723634, 2022). "Other proposed candidate genes for schwannomatosis include the coenzyme Q6, monooxygenase (COQ6) gene, and DGCR8 microprocessor complex subunit (DGCR8)." (PMID 35723634, 2022). "To date, no other studies have identified COQ6 variants in schwannomatosis patients, including our present study." (PMID 35723634, 2022). "Screening of the coding region of DGCR8, COQ6, CDKN2A, and CDKN2B was carried out, based on previous reports that point to these genes as potential candidate genes for schwannomatosis." (PMID 35723634, 2022). "Whole-exome sequencing with the genomic DNA from peripheral blood leukocytes showed that patient 1 with INF2 p.Gly73Asp had no germline, schwannomatosis-related gene variants including 22q loss of heterozygosity (LOH), NF1, NF2, LZTR1, SMARCB1, and COQ6." (PMID 39857711, 2025).
Hearing impairment (2 papers, 2020 to 2022). A decreased magnitude of the sensory perception of sound. "For the first time, COQ6 mutation with optical involvement is associated with renal and hearing impairment." (PMID 32685349, 2020). "Further studies on families segregating COQ6 biallelic variants and the establishment of animal models harboring the human genotypes are essential to uncover the audiological characteristics and pathogenic mechanism of hearing loss caused by COQ10D6." (PMID 36124066, 2022). "Specifically, no previous study (a total of 30 affected individuals with biallelic COQ6 variants from 20 families) has quantitatively analyzed the audiological phenotypes; it is thus not possible to scrutinize the audiological spectrum of COQ10D6 or the effects of CoQ10 on hearing loss." (PMID 36124066, 2022).
optic atrophy (2 papers, 2020 to 2025). A disorder characterized by loss of optic nerve fibers. "This study reports the case of two Turkish siblings with renal impairment, sensorineural deafness, and optic atrophy exhibiting COQ6 mutation." (PMID 32685349, 2020). "It is interesting to note that some patients with inherited pathogenic variants in genes implicated in primary CoQ10 deficiency manifest with optic atrophy as a feature of complex neurological phenotypes, including mutation of COQ1/PDSS1, COQ2 and COQ6." (PMID 40859035, 2025).
astrocytomas (1 paper, 2022). "Taken together, we have demonstrated that lower CoQ10 levels and protein levels of COQ3, COQ5, COQ6, COQ7, COQ8A, and COQ9 were associated with higher tumor grades and lower CS activity or COX II level in human astrocytomas." (PMID 35204836, 2022). "The levels of COQ3, COQ5, COQ6, COQ7, COQ8A, and COQ9, but not of COQ4, were lower in Grade IV astrocytoma tissues than in controls or low-grade (Grades I and II) astrocytomas, but PDSS2 levels were higher in astrocytoma tissues than in controls." (PMID 35204836, 2022).
diabetes (1 paper, 2022). "For complications in organs other than the kidney, hearing loss (66.7%) was the most common complication, followed by diabetes (48.2%) among all cases, whereas developmental disorders were frequently observed in patients with COQ2 mutation, COQ6 mutation, and mtDNA single deletion." (PMID 35257070, 2022).
focal segmental glomerulosclerosis (1 paper, 2024). A renal disorder characterized by sclerotic lesions in the glomeruli. "A podocyte-specific Coq6 KO mouse model (Nphs2-cre;Coq6loxP/loxP) was generated and described to recapitulate aspects of the pathology of focal segmental glomerulosclerosis (FSGS) observed in patients with COQ6 mutations." (PMID 38722242, 2024).
glomerular disease (1 paper, 2022). "Mutations in genes related to coenzyme Q10, another mitochondrially associated antioxidant, including PDSS1, PDSS2, COQ2, COQ6, and COQ8B/ADCK4, are associated with the development of glomerular disease." (PMID 34874915, 2022).
Hypoalbuminemia (1 paper, 2021). The concentration of albumin in the blood circulation is below the lower limit of normal. "In this study, we identified a novel compound heterozygous variant of the COQ6 gene in a nonconsanguineous Chinese family with two siblings presenting severe metabolic acidosis, proteinuria, hypoalbuminemia, growth retardation, and muscle hypotonia; the female proband also developed seizures." (PMID 35111204, 2021).
Leukoencephalopathy (1 paper, 2023). This term describes abnormality of the white matter of the cerebrum resulting from damage to the myelin sheaths of nerve cells. "Another brain pathology observed in individuals with COQ defects is disturbed myelination and leukoencephalopathy (PDSS1, COQ2, COQ6, COQ7 and HPDL)." (PMID 36978966, 2023).
Proteinuria (1 paper, 2018). Increased levels of protein in the urine. "Proteinuria caused by COQ6 gene mutation can be successfully treated with CoQ10." (PMID 30232548, 2018).
mitochondrial disease (1 paper, 2024). "In rare cases, specific therapies may exist for mitochondrial diseases caused by single-gene pathogenic variants such as COQ2, COQ6, or COQ8b." (PMID 38877226, 2024).
COQ6 also shares sentences with these, for which no sentence is quoted: Ataxia (3 papers); renal failure (3); tumor (3); benign schwannomas (2); deafness (2); Encephalopathy (2); lactic acidosis (2); autosomal recessive disease (1); cancer (1); cataract (1); cerebellar ataxia (1); chronic kidney disease (1); encephalomyopathy (1); end-stage renal failure (1); genetic disorder (1); hypertrophic cardiomyopathy (1); Intellectual disability (1); Leigh syndrome (1); MELAS (1); Mitochondrial myopathy (1); nephrosis (1); osteoporosis (1); Progressive encephalopathy (1); rectum adenocarcinoma (1); sensorineural hearing loss (1); Visual impairment (1).